ALDH2 (aldehyde dehydrogenase 2 family member)
Diseases named in the same sentence as ALDH2 in open-access papers (continued):
Sharing a sentence is not in itself a finding about the gene and the disease.
cutaneous melanoma (3 papers, 2021 to 2025). A primary melanoma arising from atypical melanocytes in the skin. "ALDH2 expression is significantly downregulated in most cancer types, including cutaneous melanoma." (PMID 40558540, 2025). "Last but not least, ALDH2 had the best prediction efficacy in assessing immunotherapeutic response compared with PD-L1, PD-1, CTLA4, CD8, and tumor mutation burden (TMB) in cutaneous melanoma." (PMID 35096916, 2021).
developmental delay (3 papers, 2008 to 2025). "Herein, we aimed to determine the involvement of ADH1B and ALDH2 gene polymorphisms in maternal alcohol consumption during pregnancy and the risk of developmental delay in offspring in a Japanese population." (PMID 39537314, 2025). "Alcohol consumption during pregnancy in mothers with the ALDH2*1/*2 genotype was found to increase the risk of developmental delays in all domains of the J‐ASQ‐3." (PMID 39537314, 2025). "We conducted a logistic regression analysis to explore the relationship between maternal drinking status during pregnancy and developmental delays in offspring with respect to maternal ADH1B (rs1229984) or ALDH2 (rs671) gene polymorphisms." (PMID 39537314, 2025). "Additionally, we found that maternal alcohol consumption during pregnancy among those with the ALDH2*1/*2 genotype increases the risk of developmental delay in all domains of the J‐ASQ‐3 at 3 years of age." (PMID 39537314, 2025). "Furthermore, in mothers carrying the ALDH2*1/*2 genotype, alcohol consumption during pregnancy was linked to an increased risk of developmental delay in five ASQ‐3 domains at 3 years of age." (PMID 39537314, 2025). "Our results suggest that alcohol consumption by pregnant females carrying the deficient variant ALDH2*2 genotype may increase the risk of developmental delay in their offspring." (PMID 39537314, 2025). "This study aimed to elucidate the impact of maternal alcohol consumption during pregnancy on developmental delays in offspring, considering the polymorphisms of ADH1B and ALDH2, using a Japanese birth cohort study." (PMID 39537314, 2025). "Effect of the combination of maternal drinking during pregnancy and ALDH2 genotype on developmental delay in the offspring at 3 years of age." (PMID 39537314, 2025).
diabetic nephropathy (3 papers, 2015 to 2025). "Although the effect of the ALDH2 SNP on diabetic nephropathy development has not been reported, the association of alcohol consumption and CKD has been studied on an epidemiological basis." (PMID 26599441, 2015).
epilepsy (3 papers, 2014 to 2024). A brain disorder characterized by episodes of abnormally increased neuronal discharge resulting in transient episodes of sensory or motor neurological dysfunction, or psychic dysfunction. "Further studies are needed to explore the exact role of ALDH2 in the process of epilepsy; for example, the association between ALDH2 and ATP-sensitive potassium channels warrants further study." (PMID 25313998, 2014). "In the present study, we first conducted a case-control study to explore the potential association between the ALDH2 rs671 polymorphism and susceptibility to epilepsy." (PMID 25313998, 2014). "According to previous reports, MiR-28 could up-regulate AQP4 (AQP4) by inhibiting aldehyde dehydrogenase 2 (ALDH2) and promote the recovery of water homeostasis after epilepsy." (PMID 37133759, 2023). "To test the possible association between ALDH2 rs671 polymorphism and PSE susceptibility, we compared the distribution of rs671 in IS patients with/without epilepsy." (PMID 25313998, 2014).
hyperuricemia (3 papers, 2020 to 2025). An abnormally high level of uric acid. "In addition, data on alcohol habits and polymorphisms in ALDH2, relevant factors in hyperuricemia and VSA, are lacking." (PMID 41156070, 2025).
insulin-dependent diabetes mellitus (3 papers, 2013 to 2021). "One study showed that alcohol intake was associated with a lower risk of all microvascular complications in a U-shaped fashion among Type 1 diabetes patients in Europe, where the ALDH2*2 allele is very rare." (PMID 24028448, 2013). "GSEA analysis indicates that the high expression groups of ALDH2, C5AR1, CFOS, IL1B, TLR2, TRXR1 jointly participate in the pathways of viral myocarditis, VEGF signaling pathway and type I diabetes mellitus associated with MI." (PMID 34799616, 2021).
memory impairment (3 papers, 2015 to 2023). "The ALDH2 gene encoding glyoxylate dehydrogenase 2 is involved in the biological process of maintaining the mitochondrial function, and memory impairment occurred in ALDH2 knockout mice." (PMID 34447367, 2021). "Unlike Aldh2-/- mice, no pathological or cognitive changes were seen in 6 month old ALDH2*2 animals, and memory impairment did not occur until 12 months (vs 3.5-4 months in Aldh2-/- mice)." (PMID 25910195, 2015).
oral cancer (3 papers, 2013 to 2021). "There is already evidence showing that deficiencies in ALDH2 are associated with an increased risk of oral cancers." (PMID 23977217, 2013). "There is accumulating evidence that the ALDH2*2 inactive mutation is highly related to alcohol-induced systemic diseases such as cardiovascular diseases, neurogenerative diseases, and upper digestive tract cancers including oral cancer." (PMID 33925003, 2021). "Association between ADH & ALDH2 variants and risk of oral cancer." (PMID 24505444, 2014). "Although alcohol is an important and established risk factor for oral cancer in India, there is a paucity of data on the association of ADH and ALDH2 variants in this population." (PMID 24505444, 2014).
oral squamous cell carcinoma (3 papers, 2017 to 2023). "Recently, genetic polymorphisms of acetaldehyde dehydrogenases (ALDH2) gene is recognized as a key factor regarding the susceptibility to both esophageal and oral squamous cell carcinomas." (PMID 28562351, 2017). "To investigate the specific isoform of ALDH that may be responsible for the increased ALDH activity observed in the cisplatin-treated cells, we examined ALDH1A1, ALDH2 and ALDH3A1 expression at the protein level in primary oral cavity squamous cell carcinoma samples from patients." (PMID 28881734, 2017).
rectal cancer (3 papers, 2002 to 2022). A primary or metastatic malignant neoplasm that affects the rectum. "ORs of 2.13 (1.0-4.7) and 1.03 (0.5-2.2) were observed for ALDH2 487Lys allele carriers among colon and rectal cancers, respectively." (PMID 12033531, 2002). "Among individuals with ALDH2 Glu/Glu genotype, high alcohol consumption was linked with a high OR for rectal cancer (OR 3.41, 95% CI 0.92-12.6)." (PMID 12033531, 2002). "In conclusion, the present study provided evidence for the possible existence of a gene-environment interaction between alcohol consumption and ALDH2 genotype for the rectal cancer in Japanese." (PMID 12033531, 2002). "Materials and Methods: A hospital-based case-control study was conducted with 72 colon and 70 rectal cancer cases and 241 non-cancer controls to evaluate the alcohol consumption and ALDH2 Glu487Lys polymorphism." (PMID 12033531, 2002).
renal fibrosis (3 papers, 2023 to 2025). A final common manifestation of a wide variety of chronic kidney diseases characterized by glomerulosclerosis and tubulointerstitial fibrosis. "Taken together, our data demonstrate that ASIV ameliorates renal fibrosis by promoting the expression of ALDH2 to regulate AKT/mTOR-mediated autophagy." (PMID 37443810, 2023). "The results show that adenine decreased the mRNA and protein expression levels of ALDH2 in rat kidneys, which was significantly reversed by ASIV, and this was further certified using immunohistochemistry analysis for ALDH2 in the renal fibrosis of rats." (PMID 37443810, 2023). "Herein, we found that ASIV ameliorated EMT and G2/M arrest, as well as promoted the expression of ALDH2 in a concentration-dependent manner in vivo and in vitro, indicating that ALDH2 might be involved in the alleviation of renal fibrosis." (PMID 37443810, 2023). "Altogether, these data suggest that ASIV might be a potential drug to alleviate the progression of renal fibrosis by directly and indirectly regulating ALDH2." (PMID 37443810, 2023). "Collectively, these results suggest that the remedial effects of ASIV on CKD rat kidneys might be involved in the alleviation of renal fibrosis, the regulation of ALDH2 expression, and the mediation of the cell cycle and autophagy." (PMID 37443810, 2023). "Similarly, immunofluorescence staining showed that the remedial effects of ASIV on renal fibrosis in TGF-β1-stimulated HK-2 cells were all blocked by ALDH2 siRNA." (PMID 37443810, 2023). "Accordingly, in the present study, we found that ASIV increased the expression of ALDH2 and inhibited autophagy by activating the AKT/mTOR pathway in the mitigation of renal fibrosis, which was further validated by small RNA interference to knock down ALDH2 in TGF-β-induced HK-2 cells." (PMID 37443810, 2023). "However, the role of ALDH2 in renal fibrosis of the CKD model is unclear." (PMID 37443810, 2023). "Herein, our new evidence suggests that it is by regulating ALDH2-mediated autophagy that ASIV mitigates EMT and G2/M arrest in renal fibrosis." (PMID 37443810, 2023). "In summary, the results of this study show that ASIV effectively treats renal fibrosis by alleviating EMT procession and G2/M arrest in vivo and in vitro, and this may be due to the ASIV-induced upregulation of the expression of ALDH2, which inhibits autophagy by regulating the AKT/mTOR pathway." (PMID 37443810, 2023).
alcoholic pancreatitis (2 papers, 2020 to 2023). Acute or chronic inflammation of the pancreas due to excessive alcohol drinking. "ALDH2 is a member of the acetaldehyde dehydrogenase family, and its gene polymorphisms are related to alcoholic pancreatitis susceptibility, particularly in Asian populations." (PMID 36820405, 2023).
allergies (2 papers, 2018 to 2024). "Our MR results, obtained by using ALDH2 rs671 and ADH1B rs1229984 as genetic IVs, showed that alcohol consumption can lead to allergic symptoms in Chinese females, and the observed negative or null association between drinking and allergy in conventional linear regression models is not causal." (PMID 39838956, 2024).
anemia (2 papers, 2016 to 2023). A reduction in the number of red blood cells, the amount of hemoglobin, and/or the volume of packed red blood cells. "The majority of Aldh2−/− Fancd2−/− mice at this age exhibit significantly reduced number of Lineage− [Lin−] c-Kit+ Sca-1+ (LKS) HSPCs but can maintain sufficient blood production to prevent symptomatic anemia." (PMID 37348497, 2023).
Aortic dissection (2 papers, 2021 to 2022). Aortic dissection refers to a tear in the intimal layer of the aorta causing a separation between the intima and the medial layers of the aorta. "ALDH2 knockout protects against aortic dissection by altering the inflammatory response and immune response and protecting elastic fibers." (PMID 36229771, 2022). "The aim of this study was to investigate the incidence of aortic dissection in different ALDH2 genotypes and explore changes in the vasculature." (PMID 36229771, 2022). "We suggest that ALDH2 KO may reduce the incidence of aortic dissection by protecting elastic fibers." (PMID 36229771, 2022).
aplastic anaemia (2 papers, 2022 to 2024). "In human, ALDH2*2 genotype has been associated with an increased risk of sporadic aplastic anemia and worse prognosis in children with idiopathic aplastic anemia." (PMID 35330099, 2022). "In line with this hypothesis, it has been shown that increased aldehyde levels due to mutations in both ALDH2 and ADH5 result in aplastic anaemia, mental retardation and dwarfism (AMed) syndrome that is characterized by neuronal clinical features that overlap with CS52,72." (PMID 38600236, 2024).
Arrhythmia (2 papers, 2016 to 2023). Any cardiac rhythm other than the normal sinus rhythm. "We also conducted a 5-year clinical longitudinal study to explore this relationship and the risk of arrhythmia among a cohort of 196 human subjects known for light-to-moderate alcohol consumption as well as the ALDH2 rs671 genotype." (PMID 37280327, 2023). "Future studies are needed to demonstrate whether these mechanisms and electrical perturbations are the causes underlying increased susceptibility of ALDH2*2 carrying human subjects who engage in chronic light-to-moderate alcohol use, to arrhythmias." (PMID 37280327, 2023). "ALDH2 KO mice had unchanged heart rhythm compared with those of controls but showed frequent ventricular ectopies, which indicate increased arrhythmia vulnerability." (PMID 26741505, 2016).
Autoimmunity (2 papers, 2020 to 2025). The occurrence of an immune reaction against the organism's own cells or tissues. "A study suggested ALDH2 as a citrullinated antigen in RA synovial tissue, potentially contributing to autoimmunity." (PMID 40868097, 2025).
bipolar I disorder (2 papers, 2014 to 2022). A bipolar disorder that is characterized by at least one manic or mixed episode. "The authors found that having bipolar disorder-II and alcohol disorder may be related to ALDH2 and ADH1B, but having bipolar disorder-I and alcohol disorder may be related only to ALDH2." (PMID 35893041, 2022).
bone marrow failure syndrome (2 papers, 2020 to 2024). "We discovered seven human families carrying genetic defects in ALDH2 and ADH5, presenting as a new bone marrow failure syndrome that is solely driven by formaldehyde accumulation." (PMID 33147438, 2020).
cardiac arrest (2 papers, 2020 to 2025). Cessation of breathing and/or cardiac function. "ALDH2 has also been confirmed to protect the brain against I/R injury induced by cardiac arrest and resuscitation in a swine model, in which the protective effect was associated with the suppression of pyroptosis." (PMID 40968356, 2025). "The activation of ALDH2 inhibits apoptosis and downregulates the excessive inflammatory response to improve acute lung injury after cardiac arrest and cardiopulmonary resuscitation in swine." (PMID 40968356, 2025). "Firstly, although we identify the significant improvement of ALDH2 on post-cardiac arrest myocardial dysfunction and 72-h survival rate in a rat cardiac arrest model, we do not assess the long-term outcome." (PMID 32292348, 2020). "In this study, we demonstrate that enhanced activity or expression of ALDH2 attenuates myocardial dysfunction, cardiomyocyte death, and mitochondrial injury in a rat cardiac arrest model." (PMID 32292348, 2020). "We explored the molecular mechanisms by which ALDH2 exerted cardioprotection after cardiac arrest through regulation of its activity in a rat cardiomyoblast hypoxia/reoxygenation model, focusing on mitochondrial ROS." (PMID 32292348, 2020). "We evaluated the effect of ALDH2 on post-cardiac arrest myocardial dysfunction through either upregulation of ALDH2 enzymatic activity or cardiac specific overexpression of ALDH2 in the animal studies." (PMID 32292348, 2020). "In this study, we evaluated the effect of enhanced activity or expression of ALDH2 on post-cardiac arrest myocardial dysfunction and survival in a rat cardiac arrest model." (PMID 32292348, 2020). "We showed that enhanced activity or expression of ALDH2 significantly improved contractile function of the left ventricle and survival rate in rats subjected to cardiac arrest-cardiopulmonary resuscitation procedure." (PMID 32292348, 2020). "Therefore, the beneficial role of ALDH2 in heart diseases is extended to the life-threatening cardiac arrest thus far." (PMID 32292348, 2020). "Moreover, ALDH2 prevented cardiac arrest-induced cardiomyocyte death from apoptosis and mitochondrial damage." (PMID 32292348, 2020). "In this study, we found that ALDH2 could reduce mitochondrial ROS, therefore protecting mitochondria and heart after cardiac arrest." (PMID 32292348, 2020). "In summary, we demonstrate that enhanced activity or expression of ALDH2 reduces cardiomyocyte death and mitochondrial injury, attenuates post-cardiac arrest myocardial dysfunction, and improves 72-h survival rate in a rat cardiac arrest model." (PMID 32292348, 2020). "To further validate the cardioprotective effect of ALDH2 activation, we examined whether enhancing the expression of ALDH2 had protective effect on post-cardiac arrest myocardial dysfunction." (PMID 32292348, 2020). "Importantly, ALDH2 restores 72-h myocardial contractile function and substantially improves the survival rate after cardiac arrest." (PMID 32292348, 2020). "Secondly, we are unable to determine definitively whether the protective effect of ALDH2 is through suppressing mitochondrial ROS production during cardiac arrest due to the technique challenge for detecting mitochondrial ROS in living organisms as accurately as in cells." (PMID 32292348, 2020). "However, the influence of ALDH2 on post-cardiac arrest myocardial dysfunction and mitochondrial ROS has not been investigated yet." (PMID 32292348, 2020).
clear cell renal cell carcinomas (2 papers, 2017 to 2024). "In renal clear cell carcinoma tissue, the expression of ALDH2 is significantly lower than that in adjacent tissues, which is also reported in HCC tissue 22,23." (PMID 39132147, 2024).
emphysema (2 papers, 2017 to 2025). "When exposed to chronic cigarette smoke, Aldh2*2 Tg mice were resistant to emphysema development, whereas influenza infection caused more epithelial damage in Aldh2−/− mice than in WT mice." (PMID 28431562, 2017). "The increase in the number of mitochondria and the upregulation of the antioxidant Prdx1 in Aldh2*2 Tg mice might also explain its resistance to CS-induced emphysema compared to the WT mice." (PMID 28431562, 2017). "More experiments are needed to elucidate the exact role of ALDH2 in the development of emphysema." (PMID 28431562, 2017). "On the other hand, we found that CS exposure neither increased the lung volume nor Lm in Aldh2*2 Tg mice suggesting that the Aldh2*2 Tg mice are resistant to emphysema development in response to CS exposure." (PMID 28431562, 2017). "Chronic exposure to CS resulted in development of signs suggestive of emphysema in WT, but not in Aldh2*2 Tg mice." (PMID 28431562, 2017).
gastro-esophageal reflux (2 papers, 2015 to 2020). "In addition, high concentration of carcinogenic acetaldehyde produced in the gastric juice of ALDH2-deficent and/or achlorhydric subjects could also be involved in the esophageal carcinogenesis through gastro-esophageal reflux of the gastric contents." (PMID 25831092, 2015).
hemorrhagic stroke (2 papers, 2021 to 2022). A stroke caused by a bleed on the brain. "Our study revealed that the ADH1B rs1229984 TC + CC genotype, but not the slow acetaldehyde metabolizing ALDH2 rs671 variant increased the risk of hemorrhagic stroke with alcohol exposure." (PMID 34051793, 2021). "However, the study did not distinguish the specific effects of ADH1B and ALDH2 genotypes on hemorrhagic stroke in alcohol-drinking patients." (PMID 34051793, 2021).
hepatitis B (2 papers, 2021 to 2022). "At first, we found that the distribution frequency of the A allele on ALDH2 rs671 was increased in patients with hepatitis B, especially in the CHB group, compared with HCs." (PMID 35237626, 2022). "It has been suggested that hepatitis B virus infection plays a selective role in this process, with the ALDH2 Glu504Lys allele being evolutionarily advantageous for hepatitis B virus carriers." (PMID 36939783, 2021). "Hepatitis B virus infection may also exert a positive selection effect on the ALDH2 Glu504Lys allele, favoring its retention." (PMID 36939783, 2021).